TNF (tumor necrosis factor)
Diseases named in the same sentence as TNF in open-access papers (continued):
Sharing a sentence is not in itself a finding about the gene and the disease.
tumor (continued). "Following continuous TNFα + IL-1β stimulation, the two TNBC cell types formed fewer cell-to-cell contacts, remained dissociated from each other and generated only small tumor cell aggregates." (PMID 34072893, 2021). "In tumor-bearing mice, the infiltration of CD8+ T cells was significantly increased and the expression of TNF-α, and IFN-γ was significantly enhanced which contributed to tumor progression after miR-326 overexpression." (PMID 34131111, 2021). "And similar findings were obtained when we analyzed correlations between the expression of TNF‐α and the levels of CD54+ neutrophils or B7‐H2+ neutrophils in tumor tissues." (PMID 34185422, 2021). "For instance, AuNPs with conjugated tumor-homing peptides encapsulated the TNF and delivered to the CD13 expressed tumor endothelium, releasing its TNF cytokines." (PMID 33503889, 2021). "In the TNBC TME, these pro-tumor immune cell types secrete cytokines such as TGF-β and tumor necrosis factor (TNF-α), which drive stemness and metastases." (PMID 35582030, 2021). "The reduced expression of FENDRR significantly decreased TNFα, and CXCL10 mRNA and protein expression, suggesting a potential role of FENDRR in tumor cell immunity." (PMID 34200642, 2021). "NK cells have been found to be dysfunctional within the tumour microenvironment (TME) of HCC with a marked reduction in interferon-gamma (IFN-γ) and TNF-α production in both the intra-tumoral and peripheral NK cell populations compared to healthy individuals." (PMID 34888493, 2021). "In WT mice, epigenetic therapy increased the number of tumor CD8+ T cells and increased the proportion of CD4+ T cells expressing IFN‐γ and TNF‐α." (PMID 33480449, 2021). "Tumor necrosis factor-α (TNF-α), a main inflammation mediator within tumor microenvironment, affects tumor development by inducing multiple chemokines to establish a complex network." (PMID 34345201, 2021). "TH1 cytokines such as IFN-γ, TNF-α and IL-2 produced by TH1 cells contribute to inhibit tumor growth and activation of tumor-specific immune mechanisms." (PMID 34012451, 2021). "Moreover, anti-tumor necrosis factor alpha and anti-IFNγ treatment counteracted the reduced tumor growth that was observed after the decrease in FAP+ cells, suggesting that FAP may inhibit the production of tumor necrosis factor alpha and IFNγ or weaken the cellular response to these cytokines." (PMID 34490078, 2021). "Cytokines including TNF-α, IFN-γ, IL-2, IL-6, and IL-12 were also increased in the PB and in tumour lesions of mice with P@aPDL1 and Vadimezan treatment." (PMID 33986264, 2021). "Our results showed a modest antitumor effect in all the tumor models evaluated, which correlated with efficient phagocytosis by DC, inducing increased CD86/40 costimulation molecules and releasing TNF-α and IL-12 cytokines." (PMID 33623783, 2021). "Based on genetic analysis, TAMs can produce various molecules, including VEGF, TNF-α, IL-1β, IL-8, platelet-derived growth factor (PDGF), thymidine phosphorylase, and MMPs that are involved in tumor angiogenesis." (PMID 33230600, 2021). "It stimulates the production of proinflammatory cytokines, such as IFN-γ and TNF-α, and activates cytotoxic T cells in the TME, thereby exerting tumor immunosuppressive effects." (PMID 35111681, 2021). "Activation of the PD1/PD-L1/L2 pathway inhibits T cell proliferation and secretion of interferon-gamma (IFN-γ), tumor necrosis factor-alpha (TNF-α), and IL-2, sustaining the immune inhibitory state of the tumor microenvironment." (PMID 34526987, 2021). "Our results show that pro-inflammatory cytokines (TNF-α, IL-12, IFN-γ and IL-2) increase in the spleen of tumour-bearing mice when treated with VES, whereas the anti-inflammatory cytokine IL-10 decreased transcriptionally." (PMID 34093795, 2021).
tumor (continued). "In this way, these cells promote tumor proliferation and growth, tissue repair and remodeling and angio- and lymphangiogenesis through the production of VEGF, TNF-α and IL-8, and exert an immunosuppressive effect on the inflammatory cells." (PMID 33146401, 2021). "Tumor necrosis factor-α (TNF-α) is produced by activated macrophages and is known as a host defense factor and inflammatory mediator that affects tumor cells." (PMID 34299102, 2021). "Tumor promoters, such as TPA and okadaic acid, commonly induce TNF-α, a pro-inflammatory cytokine, in their target organs." (PMID 33804551, 2021). "Regulated DC recognizes and phagocytoses tumor cells and induces the release of inflammatory factors such as IFN-γ, IL-2, and TNFα from immune cells." (PMID 34804019, 2021). "To test functionality of the tumor-specific T cells, we examined the IFN-gamma and TNF-α cytokine secretion capacity by restimulating SPAS-1+ CD8+ T cells on day 14 following each treatment condition." (PMID 34162858, 2021). "Among them, the caerin peptide can inhibit cancer cell behaviors by executing the TNF-α signaling pathway and can interfere with the tumor microenvironment (TME) by recruiting antigen-specific T cells to tumor sites." (PMID 33948902, 2021). "Under the stimulation of surgery, NETs can also stimulate Kupffer cells to release cytokines and chemokines, such as TNF-α, IL-6 and CXCL-10, and consequently induce tumor metastasis (Erpenbeck and Schön, 2017)." (PMID 34869390, 2021). "Tumour reduction (day 21) and elimination (day 28) when combined with rhIL-12. ↑ Serum IL-2, IFN-γ and TNF-α." (PMID 34769211, 2021). "Blocking PD-1 on ILC2s however inhibits tumor growth progression and surprisingly, induces the production of ILC2-derived TNF-α." (PMID 34531874, 2021). "Smac mimetics lead to tumor cell apoptosis when combined with agents that induce IL-1β, IFN-β, TNF-α and TRAIL." (PMID 34172082, 2021). "Neutrophils of N1 type produce more NET (neutrophils extracellular traps), ROS (reactive oxygen species) and secrete TNF-α to kill tumor cells and produce H2O2 to destroy the environment for tumor growth, inhibiting tumor metastasis." (PMID 33814009, 2021). "The results showed that TNFα, IL8, IFNγ, and GM-CSF were the most abundant pro-inflammatory cytokines secreted by CAR-T cells upon tumor engagement in a T:E ratio-dependent manner." (PMID 34093519, 2021). "Examples of cytokines and growth factors induced by TLR2 and/or TLR4 in OSCC cells include IL-1, IL-6, GM-CSF, TNF-alpha, CCL2, CCL20, CXCL8, and VEGF, which contribute to the inflammatory environment, vascularization, and tumor cell properties." (PMID 35048056, 2021). "Innate immune cells of the myeloid lineage are the principal sources of the inflammatory cytokines tumor necrosis factor (TNF), interleukin 1 beta (IL-1β), and interleukin 6 (IL-6) in the tumor microenvironment (TME)." (PMID 33808059, 2021). "M1-types are an essential part of the innate host defense system which produces pro-inflammatory cytokines such as IL-1β, IL-6, tumor necrosis factor α (TNF-α), and reactive oxygen/nitrogen species (ROS/RNS) to kill tumor cells." (PMID 34281293, 2021). "Macrophages are attracted to the circulation by various agents released from tumor cells, including CSF-1, CCL-2, VEGF, TNFα, or TGFβ, and accumulate at pre-metastatic sites." (PMID 33919517, 2021). "TNF-α is a multifunctional cytokine identified as an important mediator of cancer development, as well as induces EMT and enhances tumor angiogenesis and invasion." (PMID 35047997, 2021). "Neutrophils of N1 type are anti-tumor type and secrete many pro-inflammatory factors such as TNF-α and produce ROS and H2O2 to kill tumor cells." (PMID 33814009, 2021). "Complete elimination of MSLN+ tumour cells (~0 of normalised cell index).↑ Release of IFN-γ and TNF-α." (PMID 34769211, 2021).
tumor (continued). "In previous studies, we found that iso1Au/TNF and iso1Au/IL12 exerted maximal anti-tumor activity when injected at doses corresponding to approximately 5–15 pg of TNF and 20–70 pg of IL12, respectively." (PMID 33952242, 2021). "But the accumulation of Tregs can be prevented through dysregulation of TNF-α or TNFR2 which creates less tolerogenic environment and prevents B16F10 tumor metastasis and growth." (PMID 33986746, 2021). "TNF-α/TNFR1–mediated signals on APCs and TNF-α/TNFR2 signals on T cells are critically required for effective priming, proliferation, and recruitment of tumor-specific T cells in mice." (PMID 34199989, 2021). "Substances expressed by TANs, such as TNF-α or TNF-related apoptosis-inducing ligand (TRAIL), suppress tumor cell proliferation, induce tumor regression, or induce apoptosis in cancer cells." (PMID 34072260, 2021). "upregulation inhibits activation of γδ T cells and cytotoxicity to tumor cells by decreasing secretion of IFN-γ and TNF-α." (PMID 34804042, 2021). "The treatment of tumor-bearing mice with SCPP11 increased the thymus index and the levels of both IL-2 and TNF-α in the serum." (PMID 34203182, 2021). "NK cells trigger CSCs/undifferentiated tumor differentiation mainly through secretion and membrane-bound IFN-γ and TNF-α, and IFN-γ plays a greater role." (PMID 35096588, 2021). "While CD4+ T cells support CTLs, these cells also have direct anti-tumor activity and can kill tumors through engaging p-MHC II and secretion of IFN-γ and TNF-α effector cytokines." (PMID 33708224, 2021). "M1 macrophages, the classically activated phenotype, are stimulated by Th1 cytokines (IFN-γ and tumor necrosis factor (TNF)) and in turn exert anti-tumor effects by producing reactive nitrogen and oxygen species (ROS) and releasing pro-inflammation cytokines." (PMID 34439387, 2021). "In contrast to the unchanged percentage of TNF-α+ cells, the vast majority of splenic LSK cells and, to a lesser extent, LK cells in tumor-bearing mice produced GM-CSF." (PMID 33936078, 2021). "For example, macrophage migration inhibitory factor (MIF) is an immunomodulator that can be induced by pituitary hormones, enhancing the production of inflammatory cytokines such as TNF, IL-1, and IFN, to play its role of anti-tumor or tumor promotion." (PMID 34090476, 2021). "RGD-4C-containing TNFα and TRAIL have shown strong tumor selectivity and binding affinity, and also retain natural activities of TNFα or TRAIL." (PMID 34959463, 2021). "MCs secrete cytokines, such as tumor necrosis factor α (TNF-α) and IL-8 to stimulate immune tolerance and enhance tumor progression." (PMID 33916320, 2021). "For example, mast cells can release large quantities of tumor necrosis factor alpha (TNF-α), which leads to direct tumor cell cytotoxicity, while in other contexts TNF-α promotes tumor growth." (PMID 34063789, 2021). "We demonstrated that the mixed vaccine delayed tumor growth in animal experiments, increased the survival rate and increased the expression of the antitumor cytokines IFN-γ and TNF-α." (PMID 33792840, 2021). "When NK cells are activated, cytolytic molecules are released to induce apoptosis of tumor cells, and cytokines such as interferon-gamma (IFN-γ) and tumor necrosis factor alpha (TNF-α) are produced to regulate adaptive immune T cell-mediated immune responses." (PMID 34682815, 2021). "Normally TNF-α serves as an effector molecule capable of exerting anti-tumor immune effects through direct cancer cell killing, however TNF-α can also exert pro-tumorigenic activities in tumor cells and could be an underlying reason for observing elevated TNF-α levels in malignant MGTs." (PMID 34869014, 2021). "CD8+ T cells are a key population in the TIME for effective antitumor immunity because CD8+ T cells directly kill tumor cells by secreting effector cytokines (e.g., IFN-γ, TNF-α, and IL-2)." (PMID 34901012, 2021).
tumor (continued). "Inflammatory mediators, such as tumor necrosis factor (TNF)-α, IL-6, IL-10, and TGF-β, participate in tumor initiation and progression." (PMID 33917793, 2021). "The levels of TNF-alpha and IL1-beta and MCP-1 were increased in the tumor microenvironment from isolated rats (p<0.05)." (PMID 33411841, 2021). "Increasing immunogenic cell death of tumor cells; suppressing secretion of IFN-γ and inducing secretion of IL-6, TNF-α and TGF-β1 of tumor cells." (PMID 35002732, 2021). "CD8α ALN-1 synergizes with a neovasculature-targeted tumor necrosis factor (TNF) AcTakine, leading to complete tumor destruction and formation of immunological memory that protects against secondary tumor challenge." (PMID 34772757, 2021). "The inflammatory cytokines, including interleukin-6 (IL-6), tumor necrosis factor-alpha (TNF-α), and transforming growth factor-beta (TGF-β) play critical roles in tumor progression and promote early metastasis." (PMID 33685460, 2021). "When tested, it was demonstrated that the combination of siIDO with photothermal therapy resulted in significantly reduced tumor growth, an increase in CD4+ and CD8+ tumor infiltrating lymphocytes, reduced T cell apoptosis and increased TNF-α and IFN-γ." (PMID 34688033, 2021). "By contrast, the NK-exosome-treated tumor group exhibited a significant reduction in Bmi-1, MMP-3, IL-1β, IL-6, TNF-α, Bax, Bcl-xL, and PCNA expression compared with that in the tumor group." (PMID 34527741, 2021). "On the other hand, CD4+ T cells primarily mediate anti-tumor immunity by providing help for CD8+ CTL and antibody responses, as well as via secretion of effector cytokines such as interferon-γ (IFNγ) and tumor necrosis factor-α (TNFα)." (PMID 34084145, 2021). "CD276 is a strong immunosuppressive checkpoint that is highly expressed in numerous solid tumors, which promotes the immune escape of tumor cells from the cytotoxic effects of interferon-gamma (IFN-γ) and tumor necrosis factor-alpha (TNF-α)." (PMID 35052695, 2021). "Pretreatment with Bati significantly decreased the Met@Man-MPs-induced collagen degradation in tumor tissues by SHG microscopy, and Etan treatment significantly decreased TNF-α content in tumor tissues." (PMID 33469052, 2021). "Further, IMiDs decrease tumor-supportive BMSC cytokine signaling in the form of reduced vascular endothelial growth factor (VEGF), IL6, tumor necrosis factor alpha (TNF-a), and transforming growth factor beta (TGFB)." (PMID 34638271, 2021). "M1 macrophages also induce tumor cell apoptosis through phagocytosis, ADCC, and release of TNF and nitric oxide (NO)." (PMID 34326840, 2021). "TNF, whose mRNA is the best-characterized direct target of TTP, is involved in tumor promotion and progression in a wide range of genetic, chemically induced, and transplantable mouse models of cancer, including skin carcinogenesis." (PMID 33497366, 2021). "This increase in ubiquitin expression and proteasome activity has been suggested to be mediated by cytokines secreted by the tumor, such as proteolysis-inducing factor (PIF) and tumor necrosis factor-α (TNF-α)." (PMID 33467597, 2021). "Several pro-inflammatory cytokines, such as tumor necrosis factor-alpha (TNF-α), secreted mostly by cells of the immune system, have been shown to be upregulated in patients with ESCC, indicating their potential effect on the tumor development." (PMID 33572115, 2021). "In cancer immunotherapy, gut microbiota enhanced cancer response to the combination of CpG and anti-IL-10R through increasing tumor necrosis factor (TNF) production, which depends on the activation of TLR4 on tumor amyloid cells." (PMID 34589427, 2021).
tumor (continued). "Mast cells actively participate in tumor development by producing many proangiogenic factors, such as bFGF, VEGF, IL-8, TNF, TGF-β, and nerve growth factor (NGF)." (PMID 34209508, 2021). "Besides, myeloid-derived H2O2 activates tumor necrosis factor (TNF-α)/TNFR1 signaling in intestinal epithelial cells (IEC), increasing the recruitment of macrophages and in turn elevating the secretion of H2O2, which can trigger IEC mutation and promote tumor invasion." (PMID 34405016, 2021). "Such engineered TNFα-MSC kept the TNFα production for more than 3 months and lost their significant tumor supportive potential." (PMID 33957885, 2021). "Through immunoregulatory mechanisms, exosome-derived miR-122 drives tumor immune evasion by regulating TCR signaling and TNFα secretion." (PMID 34654454, 2021). "We have shown that CSG fused to a cytokine, TNFα, acts as a delivery agent allowing for specific binding of TNFα to tumour ECM, triggering effective immune-mediated anti-tumour effects." (PMID 34683956, 2021). "Targeting fibroblasts with high expression of fibroblast activation protein-α (FAP) in tumor-bearing mice have induced tumor necrosis mediated by IFN-γ and TNF-α, demonstrating that anti-tumor immunity has been reverted upon depletion of these cells." (PMID 34568077, 2021). "It was also reported that depletion of FAP-expressing cells in Lewis lung carcinoma tumour models triggered acute hypoxic death of both tumour cells and stroma cells, that was regulated by interferon-γ (IFN-γ) and tumour-necrosis factor-α (TNF-α)." (PMID 33806468, 2021). "For the MHC-class II-negative tumor cells, CD4+ T cells can produce a vast range of cytokines that mediate inflammatory and effector immune responses; TNF and IFN-γ are the most important cytokines that are mainly produced by T helper (Th) 1 cells." (PMID 35003090, 2021). "Consistent with the exhausted phenotype displayed by the tumor-specific TILs, IFN-γ+ TNFα+ IL-2+ tumor-specific T cells were undetectable in MC38 tumors, and on average made up only 15% of tumor-specific T cells isolated from B16.F10 tumors." (PMID 34867942, 2021). "ELISA analysis of IL‐6, TNF‐α and IFN‐γ in the serum of tumour‐bearing mice revealed a significant increase in their concentration after SEP treatment compared with NCs." (PMID 33289295, 2021). "As the immune system plays a complex role on the tumor microenvironmental (TME) battlefield, TNFα is used as a weapon to modulate and/or kill tumor cells, immune cells, and/or endothelial cells." (PMID 34445397, 2021). "Tumor necrosis factor (TNF) is used as a pro-inflammatory payload to trigger haemorrhagic necrosis and boost anti-cancer immunity at the tumor site." (PMID 34576184, 2021). "GSEA analysis showed that TNF-signaling genes were downregulated in As-T cells as compared with control cells, and in mouse SCC as compared with non-tumor skin." (PMID 33846348, 2021). "Recent report shows that growth factor such as platelet-derived growth factor (PDGF)-DD produced by tumor stimulates NK cells to secrete IFN-γ, TNF-α and chemokines by recognizing NKp44." (PMID 33920906, 2021). "It was shown that tumor clearance through GVL is dependent on both LTα and TNF expressed by donor cells, which induce apoptosis of recipient leukemic cells via TNFR1." (PMID 33917839, 2021). "The pro-inflammatory cytokines, such as interferon (IFN)-ɤ, tumor necrosis factor (TNF)-α, and interleukin (IL)-6, are well known to be key inducers for PD-L1 expression at the transcriptional level in tumor tissues." (PMID 34577564, 2021). "Activated and proliferating lymphocytes play a role in cytotoxic cell death and inhibit tumor cell proliferation and migration by secreting cytokines such as interferon gamma (IFN-γ) and tumor necrosis factor alpha (TNF-α)." (PMID 34830555, 2021).